TWIST1 (twist family bHLH transcription factor 1)
Diseases named in the same sentence as TWIST1 in open-access papers (continued):
Sharing a sentence is not in itself a finding about the gene and the disease.
lung cancer (continued). "Melatonin also suppresses lung cancer metastasis to the liver in vivo, and this action correlates with the inhibition of the EMT by downregulating Twist1 expression." (PMID 38473317, 2024). "Compared to the control group, miR-762, YAP, TWIST1, and SMAD3 expression were significantly upregulated in lung cancer patients and chronic inflammatory patients, except SMAD3 was significantly downregulated in chronic inflammatory patients." (PMID 38589525, 2024). "All studied parameters in lung cancer patients had significant difference compared to the corresponding values in chronic inflammatory patients except YAP expression, YAP protein, and TWIST1 (P = 0.784, 0.110, 0.118, respectively)." (PMID 38589525, 2024). "In EGFR-mutant lung cancer, EMT inhibits BIM through EMT-inducing transcription factors, ZEB1, and TWIST1, and becomes resistant to EGFR-TKIs19–21." (PMID 35790819, 2022). "Studies have shown that miR-33a-5p can activate Wnt/β-catenin signals through the JPX/Twist1 axis to participate in the EMT process, making lung cancer cells easy to metastasize." (PMID 35646118, 2022). "In this study, the interaction between TCF4 and TWIST1 upregulated PTHLH expression and consequently promoted lung cancer growth and cachexia." (PMID 35406121, 2022). "A recent study demonstrated that silencing of Twist1 triggered ATP depletion, leading to AMPK activation in non‐small cell lung cancer (NSCLC) cells." (PMID 36114703, 2022). "In this study, Pc-Ex, which contains emodin as a major component, sufficiently suppressed the PTHLH mRNA and PTHrP expression levels in lung cancer cells stimulated with TGFβ1 by inhibiting the interaction between TCF4 and TWIST1." (PMID 35406121, 2022). "In lung cancer, lncRNA JPX was reported to upregulate Twist1 by competitively sponging miR-33a-5p, subsequently inducing EMT and lung cancer cell invasion." (PMID 35568824, 2022). "Consistent with this, suppression of ID1 increased promoter occupancy of TCF4 and TWIST1 on E-box containing CDH1 and CDH2 promoter loci, and increased TCF4 and TWIST1 were observed on CDH1 and CDH2 promoters in FOXA1 knockdown A549 lung cancer cells." (PMID 35897813, 2022). "Previous studies have demonstrated that TCF4 can interact with TWIST1 to promote the expression of EMT-related genes, such as CDH2, VIM, SNAI1, and SNAI2, in embryonic stem and lung cancer cells." (PMID 35406121, 2022). "For example, Twist1 and ZEB1 were reported to be respectively overexpressed and downregulated in lung cancer." (PMID 35601657, 2022). "JPX promoted lung cancer cell growth and invasion via the JPX/miR-33a-5p/Twist1 axis and by activating Wnt/β-catenin signaling." (PMID 34745940, 2021). "In lung cancer, ETS1 contributes to transactivation of Twist1, a gene involved in tumour cell motility and dissemination, thereby worsening the condition." (PMID 34378314, 2021). "Based on our previous work, we have found that miR-33a-5p negatively regulated the target gene of Twist1 and participated in the EMT process of lung cancer cells." (PMID 31941509, 2020). "Our previous work showed that miR-33a-5p negatively regulated Twist1, thus inhibiting the invasion and metastasis of non-small cell lung cancer (NSCLC), and served as a potential biomarker for early lung cancer diagnosis." (PMID 31941509, 2020). "To further confirm whether Twist1 is directly involved in the Wnt/β-catenin pathway, we first screened four synthesized siRNAs and found that two of them (named si-Twist1#2, si-Twist1#4) significantly reduced the expression of Twist1 in two lung cancer cell lines." (PMID 31941509, 2020). "In this study, we obtained eight lung cancer-related genes (CDC25C, TWIST1, HIF1A, DNMT1, PARP1, CDKN1A, CCNB1, and BIRC5) as seed nodes, using an RWR algorithm analysis to prioritize lung cancer related genes." (PMID 33193600, 2020).
lung cancer (continued). "In this study, we uncover that USP4 is a novel deubquitinase of Twist1 and that silencing of Twist dramatically inhibits USP4-induced stemness of lung cancer cells, suggesting that the USP4–Twist1 axis plays a critical role in lung cancer stemness." (PMID 32549341, 2020). "Further assays revealed that JPX participated in the activation of Wnt/β-catenin signaling by regulating miR-33a-5p/Twist1, which in turn promoted the EMT process, ultimately influencing the of lung cancer process." (PMID 31941509, 2020). "Twist1 is a direct gene target of HIF-1alpha and Twist1 mediates the invasion, migration, and metastatic activity of different cancer cell types, including head and neck (HNSCC), breast, and lung carcinoma." (PMID 26823670, 2016). "For instance, the synergistic effect of Twist1 and the EGF/RAS pathway promotes tumor initiation and development in breast and lung cancer models." (PMID 26360779, 2015). "Co-culturing breast or lung cancer cells with astrocytes led to upregulated survival genes, including GSTA5, BCL2L1 and TWIST1, in tumor cells." (PMID 23426399, 2013). "Consequently, high expression of Snail, Twist1, and ZEB1 in conjunction with low expression of Smad7 and nuclear ProT was correlated with a poor prognosis in patients with lung cancer." (PMID 40259641, 2025). "Moreover, high expression of YAP gene, TWIST1, and concentration of NSE predicted poor survival in lung cancer patients." (PMID 38589525, 2024). "EMT marker Twist knockdown induces caspase-3- and -7-dependent apoptotic cell death by inhibiting the phosphorylation of EGFR, Akt, vimentin, and Twist1, and by activating E-cadherin in EGFR-TKI gefitinib and AZD9291-treated gefitinib-resistant lung cancer cells." (PMID 36768961, 2023). "Furthermore, we analyzed data from GEO (GSE19804) and found that TWIST1 (213943_at) and USP51 (229278_at) were both highly expressed in lung cancer tissues." (PMID 37422632, 2023). "Additionally, TCF4 interacts with TWIST1, promotes EMT and TGFβ1 signalling, and subsequently enhances bone metastasis in KrasG12V-driven lung cancer." (PMID 35406121, 2022). "TWIST1 was also deregulated in IPF and PAH; however, it did not appear in any LC-LD CCPs; therefore, the evidence of its association with lung cancer is not as strong as it is for RUNX2." (PMID 36551878, 2022). "The second suggests a cooperative function between RUNX2 and three transcription factors (BRCA1, FOXM1, and RUNX1) important for the specific regulation of lung cancer establishment and progression, along with three transcription factors (E2F3, FHL2, and TWIST1) of the NSCLC-GRN." (PMID 36551878, 2022). "Actually, some evidence showed that the TWIST1-related axis may participate in the EMT process by activating the Wnt/β-catenin signaling pathway, thereby accelerating the process of lung cancer." (PMID 35222014, 2021). "Additionally, JPX upregulated Twist1 by competitively sponging miR-33a-5p and subsequently induced EMT and lung cancer cell invasion." (PMID 31941509, 2020). "In the current study, we found that JPX could increase Twist1 expression by adsorbing miR-33a-5p, thereby activating Wnt/β-catenin signaling pathway to promote EMT progression in lung cancer cells." (PMID 31941509, 2020). "Additionally, Twist1,a target of miR-33a-5p, was found to be coordinately upregulated with JPX in lung cancer." (PMID 31941509, 2020). "Data on Twist1 expression in lung cancer clinical samples are limited; there are no reports on association between Twist1 expression and CSC markers." (PMID 26770215, 2016). "Moreover, IHC scoring of Twist1 and p-4E-BP1 was used to categorize the co-overexpression of Twist1 and p-4E-BP1 among the 75 lung cancer patients tested for IHC." (PMID 26360779, 2015). "Twist1 overexpression was observed in 34.7% (26 of 75) of lung cancer tissues tested, but not in the paracancerous tissues (P < 0.01)." (PMID 26360779, 2015).
lung cancer (continued). "Our results suggest that MEOX2, HDAC9, TWIST1, AhR and EVX1 overexpression from the 7p21 locus may be novel lung cancer or NSCLC tumor markers." (PMID 25460568, 2014). "In order to verify the results of immunohistochemistry, we detected the mRNA expressions of Twist1 and N-cadherin by qRT-PCR in 30 cases of lung cancer and paired nontumorous tissues." (PMID 23626784, 2013). "Of the 30 patients, 17 (56.7%) showed a higher level of Twist1 mRNA in lung cancer specimens than in nontumorous specimens and 20 (66.7%) showed a higher level of N-cadherin mRNA in cancer specimens than in nontumorous specimens." (PMID 23626784, 2013). "Furthermore, there were statistically significant differences in OS, PFS, and DMFS between patients with low and high expression of Snail, Twist1, and ZEB1, indicating that increased expression of Snail, Twist1, and ZEB1 was correlated with lung cancer progression and poor patient survival." (PMID 40259641, 2025). "Further, HDAC5 displays a significant upregulation in lung cancer and increases the proliferation and invasion of lung cancer cells through the upregulation of DLL4 (Delta-like protein 4), Notch-1 (Neurogenic locus notch homolog protein 1) and Twist-1 (Twist-related protein 1)." (PMID 35626663, 2022). "Moreover, RUNX2 is a coregulator of three of the transcriptional regulators identified in the NSCLC-GRN (i.e., E2F3, FHL2, and TWIST1), suggesting a cooperative function of these TFs in lung cancer, which has not been studied experimentally in lung cancer." (PMID 36551878, 2022). "Therefore, we considered whether an lncRNA could form a ceRNA network with miR-33a-5p and Twist1 to participate in EMT and malignant processes in lung cancer." (PMID 31941509, 2020). "It has been shown that Twist1 was not up-regulated in cisplatin-resistant lung cancer cells." (PMID 28683123, 2017). "The overexpression of TWIST1 in human lung cancers and our in vivo data from the CT-LSL OFF mouse lung tumors strongly suggested that TWIST1 may be a relevant therapeutic target in human lung cancer." (PMID 22654667, 2012). "In summary, our results demonstrate that the lncRNA JPX/miRNA-33a-5p/Twist1 axis may act as a new ceRNA regulatory network, participating in the EMT process by activating the Wnt/β-catenin signaling pathway, thus accelerating the malignant processes of lung cancer." (PMID 31941509, 2020). "Notably, epithelial–mesenchymal transition (EMT) transcription factors such as ZEB1, Slug, and TWIST1 have been identified as drivers of EGFR TKI resistance mediated by EMT, suggesting that these transcription factors could be potential targets for treating EMT-related resistance in lung cancer." (PMID 40304000, 2025). "On the other hand, we did not observe TMPRSS4-, SLUG-, or TWIST1-mediated upregulation of SOX2, in lung cancer cells (data not shown), implying that TMPRSS4 contributes to CSC functions through various molecular mechanisms depending on the cellular context." (PMID 34809669, 2021). "We further explored a potential interplay between TWIST1 reactivation and EMT in non-smoker lung cancer." (PMID 22272264, 2012).
gastric cancer (101 papers, 2007 to 2025). A primary or metastatic malignant neoplasm involving the stomach. "The EMT transcription factor Twist1 is overexpressed in gastric cancer and is associated with an increased migration and decreased sensitivity to cell death." (PMID 36781842, 2023). "An association between ETS2 and TWIST1 was also confirmed in Helicobacter pylori-infected gastric cancer cells (GCCs), where the two genes were found to enhance SIAH2 expression." (PMID 29299035, 2017). "In 195 gastric cancer samples, Twist1 expression in CAFs was associated with tumour size, invasion depth and lymph node metastasis." (PMID 28544627, 2017). "In our previous report, we demonstrated that Twist1 is frequently expressed in cancer-associated fibroblasts in gastric cancer and is associated with poor prognosis." (PMID 29029429, 2017). "Twist1 was also associated with poor prognosis in patients with gastric cancer, particularly in those with the diffuse type." (PMID 28544627, 2017). "As well, decreased PDCD4 expression was inversely associated with changed TWIST1 expression during gastric cancer (p = 0.035)." (PMID 25144746, 2014). "Here, we explored the regulation of EMT-associated proteins and PDCD4 expression in gastric cancer tissue and CagA activation of TWIST1 expression and inhibition of E-cadherin and PDCD4 expression in gastric cancer cells." (PMID 25144746, 2014). "Recent studies have shown that Twist1 Is up-regulated in gastric cancer-associated fibroblasts with poor clinical outcomes." (PMID 24204899, 2013). "For example, Dong and his colleagues combined their data with TCGA database, showing that NDRG1 regulated EMT‐associated protein expression (Twist1, Snail, VE‐cadherin and vimentin decreased, whereas E‐cadherin increased) in gastric carcinoma, which is negatively correlated with poor prognosis." (PMID 34965023, 2021). "Therefore, it is essential to identify other potential novel targets of miR-186 or Twist1-related miRNAs, which will allow us to understand the deep molecular mechanisms underlying the development and progression of gastric cancer." (PMID 27835599, 2016). "Association between expression of Twist1 or PDCD4 in gastric cancer." (PMID 25144746, 2014). "In this study, hsa-miR-495-3p was found to be underexpressed in PC with a logFC of −2.13; in a previous study, it was shown that this molecule can regulate TWIST1 and inhibit metastasis in gastric cancer." (PMID 39057123, 2024). "The activation of Twist1 by Rab31 facilitated through STAT3 stimulation and MUC-1 suppression reveals a novel Rab31/STAT3/MUC-1/Twist1/EMT axis implicated in the drug resistance and metastatic potential of gastric cancer." (PMID 39309860, 2024). "During the progression of gastric cancer, HMGA2 transactivates TWIST1 to regulate EMT of gastric cancer cells." (PMID 36945110, 2023). "Twist1 expression in CAFs is related to tumor size, lymph node metastasis, and depth of invasion, as well as poor survival in patients with gastric cancer, especially in patients with diffuse-type gastric cancer." (PMID 37143134, 2023). "MiR-15a-3p expression is down-regulated in gastric cancer to prevent the metastasis of gastric cancer through blocking Twist1 expression." (PMID 35700456, 2022). "Studies have revealed that miR-495 inhibits the expression of Twist1 and inhibits the proliferation and metastasis of gastric cancer cells." (PMID 35805066, 2022). "miR-2392 targets the regulatory operator-like protein 3 (MAML3) and NSD histone methyltransferase 1 (WHSC1) to inhibit the expression of the transcription factors Slug/Twist1 and block gastric cancer cell metastasis in vivo and in vitro." (PMID 35805066, 2022). "What’s more, phosphor-ERK, MMP2/9, N-cadherin, Vimentin, Snail, Slug and Twist1 were downregulated and E-cadherin was upregulated in gastric cancer cells upon exposure to PD98059 at 0, 5, 10, 20 μM for 24 h." (PMID 34588421, 2021).
gastric cancer (continued). "EMP3 is induced by TWIST1/2 and regulates epithelial-to-mesenchymal transition of gastric cancer cells." (PMID 33799364, 2021). "MiR-15a-3p and miR-16–1-3p negatively regulate Twist1 to repress gastric cancer cell invasion and metastasis." (PMID 34838011, 2021). "In previous research, miR-16-1-3p was found to target TWIST1 to suppress the progression of non-small cell lung cancer and gastric cancer." (PMID 34703648, 2021). "HMGA2 regulates epithelial–mesenchymal transition and the acquisition of tumor stem cell properties through TWIST1 in gastric cancer." (PMID 31249473, 2019). "Twist1 overexpression in gastric cancer cell line BGC-823 increased cell migration and decreased drug sensitivity to arsenic oxide." (PMID 30973923, 2019). "MIR-519d suppresses the gastric cancer epithelial–mesenchymal transition via Twist1 and inhibits Wnt/β-catenin signaling pathway." (PMID 31249473, 2019). "miR-16 has been demonstrated to inhibit cell invasion and metastasis via inversely regulating Twist1 in some cancers such as gastric cancer and non-small cell lung carcinoma (NSCLC)." (PMID 31572802, 2019). "Using a Twist1 monoclonal antibody to analyse gastric cancer fibroblasts, researchers in Kim′s laboratory observed Twist1 expression in CAFs more frequently than in other cancer cells but rarely observed Twist1 to be expressed in noncancerous tissue." (PMID 28544627, 2017). "Conditioned media from Twist1‐expressing skin and lung fibroblasts significantly promote invasion of gastric cancer cells in vitro." (PMID 28544627, 2017). "Knockdown of CMTM3 promoted metastasis of gastric cancer via the STAT3/Twist1/EMT signalling pathway." (PMID 29213215, 2017). "In summary, our data demonstrate that CMTM3 suppresses gastric cancer metastasis via the STAT3/Twist1/EMT pathway, which will be helpful in our understanding of the pathogenesis of gastric cancer and provide novel clues for the early diagnosis of metastasis." (PMID 27121055, 2016). "Based on the findings of the current study, it is necessary to analyze the relationship among CMTM3, p-STAT3, Twist1 expression and metastasis in gastric cancer." (PMID 27121055, 2016). "Our results showed that out of these proteins, only Twist1 is involved in the CMTM3-suppressed EMT phenotype in gastric cancer cells." (PMID 27121055, 2016). "As for the relationship between Twist1 and clinicopathologic features of gastric cancer, we observed that high Twist1 expression in GC was significantly correlated with advanced TNM stage, lymph node metastasis and tumor size (all p<0.000)." (PMID 27835599, 2016). "Taken together, knockdown of CMTM3 promoted cell migration though the STAT3/Twist1/EMT pathway in gastric cancer." (PMID 27121055, 2016). "Overall, this study demonstrates that knockdown of CMTM3 promotes the metastasis of gastric cancer through the STAT3/Twist1/EMT pathway." (PMID 27121055, 2016). "In conclusion, we for the first time demonstrated that miR-186 expression is down-regulated in gastric cancer, and overexpression of miR-186 inhibited cell proliferation, invasion and migration partially via regulation of Twist1 expression." (PMID 27835599, 2016). "Twist basic helix-loop-helix transcription factor 1 (Twist1) is frequently overexpressed in stromal fibroblasts surrounding tumors as gastric cancer cells and pharyngeal squamous cell carcinoma." (PMID 26501341, 2015). "The main findings of this study are summarized as follows: 1) H. pylori CagA is responsible for induction of TWIST1 or vimentin and inhibition of E-cadherin in gastric cancer cells." (PMID 25144746, 2014). "In gastric cancer cells cocultured with CagA expression plasmid, CagA activated TWIST1 and vimentin expression, and inhibited E-cadherin expression by downregulating PDCD4." (PMID 25144746, 2014). "Association between TWIST1 or PDCD4 expression and clinicopathological features in gastric cancer patients." (PMID 25144746, 2014).